ABCA1 (ATP binding cassette subfamily A member 1)
Diseases named in the same sentence as ABCA1 in open-access papers (continued):
Sharing a sentence is not in itself a finding about the gene and the disease.
tumor (continued). "Importantly, myeloid ablation of ABCA1 resulted in an almost 11-fold decrease in granulocytic MDSCs, Ly-6G+Ly-6CLo (median= 0.64 and 0.06 × 106 cells/gram tumor tissue in WT and A1−M/−M, respectively, p=0.04, top plot)." (PMID 29069761, 2017). "In the present study, we therefore hypothesized that mice with myeloid-specific Abca1 deletion may exhibit resistance to tumor development." (PMID 29069761, 2017). "In addition, treatment with T0901317 resulted in the upregulation of ABCA1 expression and the decline of cholesterol levels in the xenograft tumour." (PMID 26452260, 2015). "Taken together, these results suggest that ABCA1 may be a tumor suppressor and are epigenetically silenced in human cancer." (PMID 25628764, 2015). "In addition, LXR activation resulted in the upregulation of ABCA1 expression and the reduction of cholesterol levels in the xenograft tumour, suggesting that LXR exhibits anti-proliferative effects in vivo with the machinery similar to that observed in vitro." (PMID 26452260, 2015). "Moreover, we demonstrate that LXR activation reduces the growth of xenograft tumour of HOSCC cells in mice accompanied by the upregulation of ABCA1 expression and the decline of cholesterol levels in the tumour." (PMID 26452260, 2015). "However, there are few reports on the role of ABCA1 in THCA tumours." (PMID 40297807, 2025). "Furthermore, the existing body of research pertaining to the therapeutic targeting of ABCA1 in tumor treatment is limited, with a dearth of pertinent clinical trials that substantiate the potential benefits of ABCA1 targeting, specifically in terms of progression-free survival and OS." (PMID 37874419, 2023). "However, tumor-infiltrating immune cells, including myeloid cells and lymphocytes, showed high expression levels of ABCA1/G1, which increased ~3-fold in tumor-infiltrating lymphocytes and over ~7-fold in tumor-infiltrating monocytes compared to peripheral cells." (PMID 37474548, 2023). "Tumor-associated myeloid cells exhibited higher transcriptional expression of molecules linked to the “find me” (G2A), “eat me” (CD93, TIM1, SCARF1, SLC2A1, GAS6, TREM2, AXL, C1QA), and downstream processing (NR1H3, ATG7, PPARG, ABCA1, PPARD, DOCK180) phases of efferocytosis." (PMID 36439171, 2022). "Thus, we further investigated whether modulating cellular cholesterol levels significantly alters ABCA1 expression in macrophages and whether reducing ABCA1 expression levels in TAMs affects tumor progression." (PMID 36248907, 2022). "Therefore, the identification of modulators of ABCA1 might be a novel strategy to prime the tumor environment towards tumor killing." (PMID 34502100, 2021). "Thus, intracellular cholesterol imbalances mediated by ABCA1 overexpression may contribute to primary tumour growth and dissemination to distant locations." (PMID 30098223, 2018). "Recent studies suggested that ABCA1 may be a tumor suppressor." (PMID 25628764, 2015). "Single-cell analysis resolved 23 transcriptionally distinct clusters; proliferative malignant cholangiocytes selectively over-expressed ABCA1 and MAP2K1, indicating tumor-cell specificity." (PMID 41373405, 2025). "The deletion of genes encoding ATP‐binding cassette (ABC) transporter proteins, which mediate cholesterol efflux (such as ABCA1 and ABCG1), has been shown to reverse the tumor‐promoting functions of TAMs and slow tumor progression." (PMID 41020041, 2025). "ALKBH5 is an upstream target mediating the epigenetic regulation of ABCA1; it can recognize the m6A motif on the 3′ UTR of ABCA1, reduce the stability of its mRNA and the expression of its protein, thereby promoting tumor progression." (PMID 41303341, 2025).
tumor (continued). "In the context of melanoma, M1 macrophage-derived exosomal miR-29c-3p suppresses tumor migration and invasion by orchestrating cholesterol redistribution via the ENPP2-PPARγ-LXRα/β/ABCA1 signaling axis, concurrently modulating extracellular matrix remodeling." (PMID 40722703, 2025). "In contrast, ABCA1 expels isopentenyl pyrophosphate (IPP), a molecule that activates anti-tumor Vγ9Vδ2 T cells." (PMID 40370434, 2025). "The results revealed the downregulation of ABCA1 in LUAD, BRCA, OV, and LIHC tumour tissues compared with the corresponding normal tissues." (PMID 40297807, 2025). "Cholesterol efflux transporter proteins ABCA1 and ABCG1 in macrophages 33, and the cytokines secreted by tumor cells including CTSK34, IL-10 and CSF135, have been shown to trigger the polarization of TAMs towards the M2 phenotype." (PMID 38993570, 2024). "Mechanically speaking, ALKBH5 recognized the m6A motif on ABCA1 3'UTR, lowering its mRNA stability and protein expression to facilitate tumor advance." (PMID 38481816, 2024). "To further investigate cholesterol metabolism in GBMs, we examined the expression patterns of APOA1 and ABCA1/G1 on GBM cells and tumor-infiltrating immune cells." (PMID 37474548, 2023). "ABCA1 is highly expressed not only in BCPAP cells with high cell invasion and mobility but also in BCPAP-bearing tumor tissues." (PMID 36672209, 2023). "We therefore exploit ectopic expression of the ABCA1/G1 ligand ApoA1 to enhance cholesterol efflux from TAMs in the GBM microenvironment, which leads to a TAM-T-cell-mediated tumor clearance." (PMID 37474548, 2023). "Downregulation of ABCA1 levels can promote TAM polarization towards an inflammatory phenotype and control tumor growth." (PMID 36248907, 2022). "We therefore evaluated the levels of ABCA1 expression in a panel of EOC cell lines using RT-qPCR and compared them to those in a cohort of EOC patient tumours (150 serous and 80 endometrioid tumours)." (PMID 35454786, 2022). "We found that the mRNA expression levels of ABCA1 and MTHFD2 genes in TAMs increased significantly with tumor progression." (PMID 36248907, 2022). "Deletion of cholesterol efflux genes ATP-binding cassette transporter A1 (ABCA1) and ATP-binding cassette transporter G1 (ABCG1) in peritoneal TAMs has been found to significantly impair tumor progression." (PMID 36035994, 2022). "The genetic deletion of ABCA1 and/or ABCG1 revert the tumor-promoting functions of TAMs and reduces tumor growth." (PMID 33391518, 2021). "ABCA1 is a CHO efflux-related gene; PPARδ directly increases the levels of ABCA1 mRNA and membrane CHO expression, which is followed by tumor growth." (PMID 34775964, 2021). "The ATP Binding Cassette transporter A1 (ABCA1) effluxes isopentenyl pyrophosphate (IPP), a strong activator of anti-tumor Vγ9Vδ2 T-cells." (PMID 32155954, 2020). "Especially, the candidates ABCA1, MET, and SCD were entangled with tumor metabolism, while FCGR1A and ITGB2 showed the widest interactions with immunological processes." (PMID 32228647, 2020). "The expression level of ABCA1 and SLC7A11 has been evaluated in three independent tumor nodules treated with DMSO or fendiline/cisplatin; results showed a significant inhibition of their transcription." (PMID 33182713, 2020). "Specifically, LXRα and the ABC-cholesterol transporter; ABCA1, a direct target gene of LXR, were significantly upregulated in TNBC tumor-resident immune cells." (PMID 31863071, 2019). "This study broaden the prognostic value of ABCA1, ACSL1, AGPAT1 and SCD genes, independently of CRC tumor stage, leading to future precision medicine approaches and “omics”-guided therapies." (PMID 29464044, 2018).
tumor (continued). "Importantly, loss of myeloid Abca1 alone was sufficient to significantly inhibit tumor development (p=0.01), and additional deletion of Abcg1 in the same immune cells did not lead to enhanced suppression of tumor growth." (PMID 29069761, 2017). "Changes in cholesterol metabolism or levels of components of cholesterol homeostasis namely apoA-I/HDL, ABCA1, ABCG1, and SR-B1 are known to affect immune responses which in turn impact anti-tumor effects." (PMID 26617517, 2015). "Another study reported that knockdown of astrocytic ATP-binding cassette transporter A1 (ABCA1), which is responsible for cholesterol trafficking, with the injection of Gfap-shAbca1 into GL261-bearing mice led to decreased tumor cholesterol and induction of apoptotic cell death." (PMID 40745073, 2026). "It was concluded that downregulating ABCA1 levels could promote TAM polarization to an inflammatory phenotype and control GBM tumour growth." (PMID 40297807, 2025). "The present study evaluated the expression of Cholesterol transporter [importer -Lipoprotein Receptor-related Protein-1 (LRP-1) and exporter -ATP-binding cassette transporters-1 (ABCA-1)] in GBM and their implications in tumor-biology, clinical outcome and therapeutic potentials." (PMID 36267880, 2022). "Apart from the tumor cells, endothelial cells (normal and proliferating endothelial cells) also showed positivity for ABCA-1 without a significant difference in the intensity." (PMID 36267880, 2022). "In line with this, variations in intracellular cholesterol levels mediated by ABCA1 overexpression drive the onset of EMT and the promotion of tumor invasiveness, whilst human solid tumors at advanced stages are characterized by high levels of ABCA1 expression." (PMID 34109128, 2021). "Lack of Abca1 inhibited tumor bed accumulation of myeloid derived suppressor cells, known to promote tumor angiogenesis, metastasis and immune evasion, resulting in tumor growth inhibition." (PMID 33562440, 2021). "ABCA1 correlated with LXRA (Pearson’s correlation: R = 0.502: p < 0.0001) in ER-negative but not in ER-positive tumours." (PMID 31683867, 2019). "Both ABCA1 and APOE were assessed for correlation with NR1H2/LXRB and whilst APOE weakly correlated with NR1H2/LXRB in ER-positive tumours (R = 0.25) it was not correlated in ER-negative tumours; ABCA1 was not correlated with NR1H2/LXRB in either tumour type." (PMID 31683867, 2019). "Moreover, this study highlights the utility of ABCA1 and AGPAT1 as prognosis biomarkers of recurrence in CRC, independently of tumor stage." (PMID 29464044, 2018). "Abcg1−M/−M (G1−M/−M) animals were also protected by 2.5-fold relative to WT, with no further inhibition of tumor growth in Abca1/Abcg1 myeloid-specific double knockout animals (DKO)." (PMID 29069761, 2017). "In contrast, another group cultured LNCaP xenografts in castrated mice, finding that ABCA1 and SR-BI expression was increased in the castration-resistant tumours, but ABCG1 expression was not investigated." (PMID 23320115, 2013).
tumor (continued). "Notably, AKR1B1, CD36, ABCA1, PRKD1, OSBPL1A, and FABP3 showed varied expressions in specific cells, suggesting their significant roles in STAD carcinogenesis, further confirmed by elevated mRNA levels in tumor tissues via qRT-PCR." (PMID 38440405, 2024). "ABCA1 was primarily expressed by macrophages and in tumor tissues, not normal gastric tissues." (PMID 37874419, 2023). "Indeed, while several studies have evaluated ABCA1 expression at the tumor tissue level, there is a lack of research at the single-cell level, nor is it clear how ABCA1 impacts the tumor microenvironment (TME)." (PMID 37874419, 2023). "However, the functional role for alternative cholesterol efflux transporters, ABCA1 and SR-B1, in tumor growth and host immune surveillance, has not yet been reported." (PMID 29069761, 2017). "Thus, ABCA1 could favour tumorigenesis by promoting the growth of the primary tumour, by increasing proliferation and the formation of distant lesions, by inducing EMT and by the subsequent mobilization of tumour cells." (PMID 30098223, 2018). "Finally, to determine whether ABCA1 can be an effective target for the treatment of IDHWT GBMs, we performed a lovastatin treatment experiment in the orthotopic GL261IDH1-WT-Luc model and showed that this modulation of immune metabolism can significantly control tumor progression." (PMID 36248907, 2022). "Although deficiency of ABCA1 or ABCG1 transporters does not always mirror the ApoA-I effect, at first glance, it seems counterintuitive that deficiency of ABCA1 and excess of ApoA-I, which affect RCT in opposite directions, both may contribute to tumor suppression." (PMID 31374929, 2019). "The lower numbers of MDSCs in animals with myeloid ablation of ABCA1 and ABCG1 was specific to the tumor compartment as these cells were not decreased in the spleen of receptor knock-out mice relative to WT animals." (PMID 29069761, 2017). "We analyzed the TCGA-LUAD dataset (n = 585): after excluding 8 cases because of the lack of information about tumor stage and 59 cases classified as “normal tissues”, we analyzed the expression of TFEB, ABCC1 and ABCA1 mRNA in the remaining cohort of 531 cases of primary tumors." (PMID 39107857, 2024).
cancer (104 papers, 2008 to 2026). A tumor composed of atypical neoplastic, often pleomorphic cells that invade other tissues. "An intriguing corollary here is the potential utility of ABCA1 expression as a diagnostic marker to identify cancers that would be sensitive to targeting the Chol/SM imbalance." (PMID 41521893, 2026). "ABCA1 is closely associated with the development of various human cancers, including thyroid, pancreatic, ovarian, and breast cancers." (PMID 36672209, 2023). "We observed increased expression of ABCA1 in BCPAP cells because ABCA1 is known to be associated with a malignant phenotype in several types of cancers." (PMID 36672209, 2023). "The role of the cholesterol efflux channel ABCA1 in cancer is controversial, having been associated with a range of sometimes conflicting phenotypes across diverse conditions and cancer types." (PMID 35327383, 2022). "In contrast, other studies proposed mechanisms associated with ABCA1 activity in favor of cell cancer proliferation." (PMID 33562440, 2021). "In other words, ABCA1 downregulation causes Akt upregulation, which in turn promotes cancer cell growth." (PMID 33562440, 2021). "On one hand, diminished ABCA1 expression in neoplastic breast and prostate tissue was associated with an increased rate of cancer cell proliferation." (PMID 33562440, 2021). "ABCA1 exhibits anticancer activity that inhibits the expression of the ABCA1 gene through functional mutations in oncogenes or cancer-specific ABCA1." (PMID 32194787, 2020). "ABCA1 deficiency in conjunction with the high cholesterol synthesis found in cancer cells can lead to increased mitochondrial cholesterol, thereby promoting cancer cell survival." (PMID 32194787, 2020). "ABCA1 deficiency causes an increase in mitochondrial cholesterol content, which promotes survival of cancer cells." (PMID 30283400, 2018). "Therefore, in general, ABCA1 is associated with cancer proliferation, invasion, metastasis, and changes in cancer treatment." (PMID 40297807, 2025). "Likewise, ABCA1 downregulation caused by ABCA1 promoter hypermethylation led to elevated cholesterol levels in cancer cells, enhanced cell proliferation, and inhibited apoptosis." (PMID 38481816, 2024). "Deficiency of ABCA1, a main receptor mediating cholesterol efflux, increases mitochondrial cholesterol, inhibits release of mitochondrial cell death-promoting molecules, and thus facilitates cancer cell survival." (PMID 37089950, 2023). "Moreover, as a result of the intricately orchestrated sequence of oncogenic gene mutations in cancer, which give rise to diverse metabolic modifications, ABCA1 has been recognized as a gene that exhibits a synergistic response." (PMID 37874419, 2023). "To determine whether the EMT regulatory signaling pathway is dependent on ABCA1 expression, we identified the most aberrantly activated pathways, including the EGFR, SRC, and ERK pathways, which are associated with ABCA1 in various carcinomas." (PMID 36672209, 2023). "Likewise, ABCA1 downregulation caused by ABCA1 promoter hypermethylation, miR-183 degradation or loss of function mutations, led to elevated cholesterol levels in cancer cells, enhanced cell proliferation and inhibited apoptosis." (PMID 33562440, 2021). "Thus, we wanted to know if RASSF1C over-expression also up-regulates ABCA1 which has been linked to cancer cell drug resistance." (PMID 30719208, 2019). "Unidirectional, partially ABCA1-driven cholesterol efflux via disc-shaped rHDL particles might thereby cause depletion of cellular cholesterol pools, eventually leading to decreased proliferation and viability of cancer cells." (PMID 35577388, 2022). "To investigate the clinical relevance of ABCA1 upregulation in cancers, we analyzed ABCA1 expression in cancer using the UCSC Xena platform." (PMID 41521893, 2026). "Comparative ABCA1 expression data of both normal tissue and primary tumors were available for 24 cancer subtypes in the GDC TCGA database." (PMID 41521893, 2026).